HDAC9 (histone deacetylase 9)
Diseases named in the same sentence as HDAC9 in open-access papers (continued):
Sharing a sentence is not in itself a finding about the gene and the disease.
Cognitive impairment (41 papers, 2012 to 2025). Abnormal cognition is characterized by deficits in thinking, reasoning, or remembering. "Further studies on the interaction between miR-182 and HDAC9 may shed light on the regulation of cognition and cognitive disorders." (PMID 27558292, 2016).
ischemic stroke (39 papers, 2012 to 2025). A stroke disorder caused by obstruction of blood flow to the brain, due to thrombotic (local blood clot formation) or embolic (due to a blood clot or other material traveling from another site) event. "Genetic variations in some genes (e.g., SLC22A7, ZNF318 and HDAC9) were also associated with ischemic stroke." (PMID 35345488, 2022). "HDAC9 genetic variants mediate their effects through increased HDAC9 expression and increased ischemic stroke risk by promoting carotid atherosclerosis." (PMID 35345488, 2022). "The previously reported GWAS associations from a recent ischaemic stroke meta-analysis (9p21, HDAC9, PITX2, ZFHX3) were all found to be more significant using the age-at-onset informed approach than the uninformed analysis." (PMID 25078452, 2014). "In addition, MMP12 and HDAC9 gene expression levels were associated with risk of ischemic stroke, and inhibition of the expression of these genes inhibited plaque development and promoted plaque stability." (PMID 35842645, 2022). "GWS association of ischemic stroke with an HDAC9 variant was identified by GWAS." (PMID 29458411, 2018). "Recently, several GWASs identified a novel association between HDAC9 and ischaemic stroke." (PMID 28145521, 2017). "Moreover, HDAC9 is also a common genetic variant that shares genetic susceptibility to ischemic stroke and coronary artery disease (CAD)." (PMID 27642596, 2016). "Moreover, HDAC9 expression was upregulated in human atherosclerotic plaques and was also a common genetic variant that shares the genetic susceptibility to ischemic stroke and coronary artery disease." (PMID 27642596, 2016). "Interestingly, a genome-wide association study indicated that HDAC9 played a critical role in the development of ischemic stroke, and its variants could increase the risk of ischemic stroke by promoting carotid atherosclerosis." (PMID 36185600, 2022). "Several genes, including PITX2,ZFHX3, HDAC9, FOXF2,GUCY1A3, and GCH1, havebeen identified to increase the risk of developing ischaemic stroke." (PMID 40351662, 2025). "Methylation of AMH, C17orf82, HDAC9, IGFBP3, LRRC10B, PDE3A, PRDM6, SYT7 and TBX2 was significantly associated with ischemic stroke." (PMID 35345488, 2022). "As it is known that hypermethylation always suppresses gene expression, the findings of hypomethylated HDAC9 in ischemic stroke patients in our study were consistent with previous findings from studies on gene expression." (PMID 35345488, 2022). "In this study, we developed a relevant hiPSC-derived SMC model to assess the phenotypic effect of the most strongly associated GWAS hit for ischemic stroke in the HDAC9 gene, and to test HDAC inhibitors for potential therapeutic interventions." (PMID 35433850, 2022). "Higher methylation levels of 18 targets in AMH, C17orf82, HDAC9, IGFBP3, LRRC10B, PDE3A, PRDM6, SYT7 and TBX2 genes were associated with a lower risk of ischemic stroke." (PMID 35345488, 2022). "According to the results from stage one and stage two, we confirmed that higher methylation levels of 17 targets in AMH, C17orf82, HDAC9, IGFBP3, LRRC10B, PDE3A, PRDM6, SYT7 and TBX2 genes were associated with a lower risk of ischemic stroke." (PMID 35345488, 2022). "At present, our research group is elucidating the role and molecular mechanisms of HDAC9 in ischaemic stroke." (PMID 23480850, 2013). "Recently, the Wellcome Trust Case Control Consortium 2 ischemic stroke GWAS identified a novel association at 7p21; the most likely underlying gene is HDAC9, encoding histone deacetylase 9.This association was confined to the large artery stroke subtype." (PMID 23016624, 2012). "In addition, IGFBP3 and HDAC9 have been found to be related to poor prognosis in patients with ischemic stroke." (PMID 35345488, 2022). "A recent clinical study revealed that inhibiting HDAC9 might be a target for secondary prevention of ischemic stroke." (PMID 34707480, 2021).
ischemic stroke (continued). "Histone deacetylase 9 (HDAC9) has recently been demonstrated as a key regulator of vascular smooth muscle cell (VSMC) phenotype and is associated with abdominal aortic calcification, myocardial infarction, and ischemic stroke." (PMID 32585591, 2020). "Furthermore, HDAC9 was found to promote MAPK-mediated NF-κB phosphorylation in ischemic stroke." (PMID 35433850, 2022). "In this prospective population study of 335,146 adults enrolled in the UK Biobank, the abdominal aortic calcification-associated risk allele of a genetic variant in HDAC9 was associated with increased risk of systolic hypertension, non-ST segment elevation myocardial infarction, and ischemic stroke." (PMID 32585591, 2020). "Therefore, inhibiting HDAC9 might offer a novel secondary preventative treatment for ischemic stroke." (PMID 29247141, 2018). "Therefore, it is necessary to further clarify the role of HDAC9 on the regulation of neuronal function and whether autophagy in neurons shares the same mechanisms as BMVECs regulated by HDAC9 in ischaemic stroke." (PMID 26865248, 2016). "The HDAC9 enhances the transcriptional activity of HIF-1 by catalyzing its deacetylation, thereby mediating ischemic stroke-induced neuronal iron death in the cortical layer." (PMID 39876842, 2024). "HDAC9 enhances the transcriptional activity of HIF-1 by catalyzing HIF-1 deacetylation, thereby mediating ischemic stroke-induced neuronal Ferroptosis in cortical layers." (PMID 39876842, 2024). "The results showed that the mean methylation levels of AMH, C17orf82, HDAC9, IGFBP3, LRRC10B, PDE3A, PRDM6, SYT7 and TBX2 were significantly (Wilcoxon's two sample test) lower in ischemic stroke cases than in controls." (PMID 35345488, 2022). "However, the role of HDAC9 in ischaemic stroke keeps unknown." (PMID 26865248, 2016). "However, the molecular pathways that are affected by the identified genetic variants are not yet pinpointed, and the role of HDAC9 is ischaemic stroke keeps unknown." (PMID 23480850, 2013). "Silencing HDAC9 has been shown to reduce infarct size, suppress pro-inflammatory cytokine expression (e.g., IL-1β, TNF-α, IL-6), and improve neurological function, underscoring its potential as a therapeutic target in ischemic stroke." (PMID 40867911, 2025). "In addition, certain molecular genetic variations have been shown to be closely related to ischemic stroke, such as Paired-like homeodomain transcription factor 2 (PITX2), Histone deacetylase 9 (HDAC9), and Zinc finger homeobox protein 3 (ZFHX3)." (PMID 32228489, 2020). "This study provides some support for the hypothesis that HDAC9 is important in the pathogenesis of ischemic stroke and that its inhibition, by SVA or a more specific HDAC9 inhibitor, is worthy of evaluation as a treatment to prevent recurrent ischemic stroke." (PMID 29247141, 2018). "This supports the hypothesis that HDAC9 is important in the ischemic stroke pathogenesis and that its inhibition, by SVA or a more specific HDAC9 inhibitor, is worthy of evaluation as a treatment to prevent recurrent ischemic stroke." (PMID 29247141, 2018).
liver cancer (39 papers, 2016 to 2025). An epithelial or non-epithelial malignant neoplasm that arises from the liver. "Analysis of 373 liver cancer datasets revealed that the expression profile of HDAC9 positively correlated with those of stemness-related genes, mesenchymal genes, and cell-cycle regulators." (PMID 32977608, 2020).
medulloblastoma (39 papers, 2011 to 2025). A malignant, invasive embryonal neoplasm arising from the cerebellum. "Diseases associated with HDAC9 include gastrointestinal neuroendocrine tumor, medulloblastoma and cutaneous squamous cell carcinoma." (PMID 30563222, 2018). "HDAC5 and HDAC9 are valuable markers for medulloblastoma risk stratification and are potential novel drug targets." (PMID 27177225, 2016). "In medulloblastoma, HDAC5 and HDAC9 up-regulation has been associated with poor prognosis and HDAC inhibitor treatment resulted in down-regulation of the Dickkopf-1 tumor-suppressor through antagonizing Wnt signaling in cultured medulloblastoma cells." (PMID 23951168, 2013). "Recent studies have suggested that HDAC5 and HDAC9 are significantly upregulated in high-risk medulloblastoma in comparison with low-risk medulloblastoma and be associated with poor survival 6.It also has been reported that HDAC2 expression is significantly associated with CRC progression." (PMID 35399729, 2022). "Likewise, upregulated expression of HDAC9 is associated with poor survival in medulloblastoma patients and in childhood acute lymphoblastic leukemia patients." (PMID 25760078, 2015). "Studies of HDAC9 have revealed its association with medulloblastoma and schizophrenia." (PMID 25575711, 2015). "HDAC5 and HDAC9 expression rise in high-grade medulloblastoma, compared to low-grade medulloblastoma and abnormal tissues." (PMID 36146527, 2022). "H3 acetylation levels are elevated in high-grade astrocytoma compared to low-grade medulloblastoma and normal brain tissues, as are the expression of HDAC5 and HDAC9 in high-grade medulloblastoma." (PMID 30498431, 2018). "In human medulloblastoma, HDAC5 and HDAC9 upregulation were identified as markers for tumors with poor prognosis." (PMID 23951168, 2013). "In medulloblastoma patients, aberrant expression of HDAC5 and HDAC9 have been correlated with poor clinical outcome." (PMID 23951168, 2013). "Similarly, it has been shown that the transcription level of HDAC9 (belonging to the class IIa HDAC family) is remarkably increased in different types of cancers, including glioblastoma, medulloblastoma, cervical cancer, and acute lymphoblastic leukemia." (PMID 31013819, 2019).
colitis (38 papers, 2011 to 2025). Inflammation of the colon. "In that model, colitis was associated with increased local expression of HDAC9, and HDAC9 KO mice were resistant to the development of pathology." (PMID 34318404, 2021). "Similarly, deficiency of HDAC9 enhanced regulatory T cell numbers and ameliorated models of systemic lupus erythematosus and colitis." (PMID 33123128, 2020). "Furthermore, the induction of colitis in mice was associated with increased HDAC9 expression, while the Hdac9 knock-out mice were resistant to development of colitis." (PMID 30792714, 2019). "Hdac9 expression is increased in colon after induction of colitis and Hdac9-/- mice are resistant to colitis development." (PMID 33513699, 2021). "In models of colitis, strategies to reduce HDAC9 expression enhance the function of Tregs and prevent colitis." (PMID 31849938, 2019). "The role of Hdac9 as modulator of Treg functions was confirmed in a model of colitis." (PMID 33513699, 2021). "In addition, increased SCFAs could enhance the differentiation of peripheral Treg populations through HDAC9 inhibition and, consequently, attenuation of colitis in mice." (PMID 33348596, 2020). "Therefore, HDAC9 inhibition could potentially be responsible for the increased Treg cell numbers and the protective effect in colitis development in these mice treated with TSA and SAHA." (PMID 30792714, 2019).
Hypertension (35 papers, 2009 to 2025). The presence of chronic increased pressure in the systemic arterial system. "In summary, the present study showed that DNA methylation in the promoters of PRDM6, HDAC9, IGFBP3, LRRC10B, SYT7, PDE3A, TBX2 and C17orf82 genes were significantly associated with BP or hypertension." (PMID 35087571, 2021). "We found that DNA methylations in the promoters of PRDM6, HDAC9, IGFBP3, SYT7, TBX2 and C17orf82 were significantly associated with BP or hypertension in the Chinese Han population." (PMID 35087571, 2021). "SNP, rs12155400, in the histone deacetylase 9 gene (HDAC9) on chromosome 7, was associated with retinopathy in analysis of participants without hypertension, −1.3±0.23 (beta ± standard error), p = 6.6×10−9." (PMID 23393555, 2013).
renal fibrosis (34 papers, 2013 to 2024). A final common manifestation of a wide variety of chronic kidney diseases characterized by glomerulosclerosis and tubulointerstitial fibrosis. "The correlation between HDAC9 and renal fibrosis is less studied, however, HDAC9 has been shown to promote vascular endothelial cell injury by acting on the p38 MAPK pathway." (PMID 36148005, 2022).
heart failure (33 papers, 2010 to 2025). Inability of the heart to pump blood at an adequate rate to meet tissue metabolic requirements. "HDAC9 can be detected in advanced heart failure stages, and a higher cardiac function grade correlates with greater HDAC9 expression levels, indicating that HDAC9 is positively correlated with the severity of heart failure." (PMID 38584203, 2024). "HDAC9 shows the best potential as an indicator of the severity of heart failure." (PMID 38584203, 2024). "Hence, alterations in HDAC9 expression could serve as potential biomarkers for assessing the severity of heart failure." (PMID 40497340, 2025).
osteosarcoma (33 papers, 2007 to 2025). A usually aggressive malignant bone-forming mesenchymal neoplasm, predominantly affecting adolescents and young adults. "Overexpression of HDAC9 in osteosarcoma cells promotes cell proliferation and invasion." (PMID 34318404, 2021). "HDAC9 is upregulated in osteosarcoma cell lines (e.g., U2OS and MG63) and in osteosarcoma tissues." (PMID 34318404, 2021).
B-cell lymphoma (29 papers, 2012 to 2025). "Interestingly, in vitro acquired resistance to ricolinostat, a selective HDAC6 inhibitor, was associated with higher HDAC9 expression in a B-cell lymphoma cell line, and HDAC9 expression has been associated with drug resistance and poor prognosis in a variety of solid malignancies." (PMID 32872487, 2020). "HDAC9 is highly expressed in human B-cell lymphomas and transgenic mice over-expressing Hdac9 develop, with age, lymphoproliferations and B-cell lymphomas." (PMID 33513699, 2021). "We therefore sought to characterize HDAC9 expression in human B-cell lymphomas and establish whether aberrant expression can drive B-cell lymphoma in a genetically engineered mouse (GEM) model." (PMID 27799148, 2016). "HDAC9 is highly expressed in B-lymphoproliferative disorders, including in B-cell non-Hodgkin lymphoma (B-NHL) cell lines and patient samples, suggesting that its deregulation might lead to abnormal B-cell proliferation." (PMID 27799148, 2016). "It remains to be established whether mutant MEF2B can drive HDAC9 expression in B-cell lymphomas, but recent research has identified a novel MEF2D–BCL9 fusion protein associated with high-risk acute B-cell precursor lymphoblastic leukemia (ALL) that directly upregulates HDAC9." (PMID 27799148, 2016). "Histone deacetylase 9 (HDAC9) is expressed in B cells, and its overexpression has been observed in B-lymphoproliferative disorders, including B-cell non-Hodgkin lymphoma (B-NHL)." (PMID 27799148, 2016). "In contrast, low-grade B-cell lymphomas, as well as CHL, showed low HDAC9 expression in tumor cells when nuclear intensity was compared with that of adenocarcinoma cells as a positive control (P=0.004, Fisher's exact test)." (PMID 27799148, 2016).
myocardial infarction (28 papers, 2012 to 2025). Gross necrosis of the myocardium, as a result of interruption of the blood supply to the area, as in coronary thrombosis. "The BP-associated genetic locus rs2023938 of HDAC9 has been shown to overlap myocardial infarction-associated CpG sites." (PMID 35087571, 2021). "Subsequent analyses indicated correlations of the lead SNP in this locus, rs2107595, with HDAC9 mRNA expression and plasma HDAC9 levels in controls and patients with myocardial infarction." (PMID 35714152, 2022). "Likewise, higher expression of HDAC9 (histone deacetylase 9) was associated with higher concentrations of pro-inflammatory macrophages within atherosclerotic plaques, a common variant at this locus being associated with vascular calcifications and myocardial infarction risk." (PMID 36247456, 2022). "Our results suggest a role of HDAC9 in myocardial infarction through non-coronary plaque-related, possibly stenotic, hypertensive, or calcific aortic pathology." (PMID 32585591, 2020). "Female mice lacking HDAC5 or HDAC9 are protected from post-myocardial infarction (MI) remodeling due to enhanced estrogen receptor-mediated transcription of proangiogenic genes in the heart whereas male knockout mice die at a higher frequency post-MI." (PMID 24608696, 2014).
Cerebral ischemia (27 papers, 2012 to 2025). Restriction of arterial blood supply to the brain associated with insufficient oxygenation to support the metabolic requirements of the tissue. "A previous study reported significant upregulation of HDAC9 expression in the ischemic hemisphere of rat brains following cerebral ischemia-reperfusion injury." (PMID 40356977, 2025). "In rat cerebral ischemia/reperfusion injury, the brain injury can be alleviated by silencing the HDAC9 gene by lentivirus recombination in the brain with upregulated HDAC9." (PMID 32963637, 2020). "Moreover, HDAC9 has been shown to induce inflammatory responses, apoptosis, and abnormal permeability of endothelial cells in cerebral ischemia/reperfusion injury." (PMID 37573538, 2024). "Indeed, HDAC9 is overexpressed in neurons after brain ischemia where exerts a neurodetrimental role." (PMID 37324938, 2023). "Indeed, brain ischemia induced an up-regulation in HDAC9 protein levels that binds to the two transcription factors HIF-1 and Sp1 causing their deacetylation." (PMID 37324938, 2023). "For example, HDAC9 expression is increased in endothelial cells during cerebral ischemia/reperfusion injury in rats, promoting endothelial dysfunction through an increased inflammatory response, apoptosis, and cell permeability through decreased cell-cell junction proteins." (PMID 34338228, 2021). "Among the HDAC isoforms, HDAC9 has emerged as a key contributor to endothelial injury and blood–brain barrier (BBB) disruption in the context of cerebral ischemia/reperfusion injury." (PMID 40867911, 2025).
pulmonary fibrosis (27 papers, 2015 to 2025). Chronic progressive interstitial lung disorder characterized by the replacement of the lung tissue by connective tissue, leading to progressive dyspnea, respiratory failure, or right heart failure. "In contrast to HDAC4 and HDAC7, much less is known about the role and functions of HDAC5 and HDAC9 in lung fibrosis." (PMID 35626663, 2022).
schizophrenia (27 papers, 2009 to 2025). A major psychotic disorder characterized by abnormalities in the perception or expression of reality. "Studies focused on the neuropathology of schizophrenia have specifically implicated the neuronal protective role of HDAC9." (PMID 34318404, 2021). "Structural variants including deletions and copy number variants in HDAC9 have been identified in patients with schizophrenia and patients with autism." (PMID 29458411, 2018). "In addition, PARD3 and HDAC9 have been both implicated in mental disorders such as schizophrenia." (PMID 29631039, 2018). "Another study identified the genes associated with the antipsychotic treatment response in schizophrenia patients (DNMT3A rs2304429, HDAC5 rs11079983, HDAC9 rs1178119)." (PMID 36979236, 2023). "For example, hemizygous deletions of HDAC9 have been identified in a small fraction of schizophrenia patients." (PMID 34318404, 2021).